MCM4 (minichromosome maintenance complex component 4)
Diseases named in the same sentence as MCM4 in open-access papers (continued):
Sharing a sentence is not in itself a finding about the gene and the disease.
tumor (continued). "Moreover, the independent prognostic analysis showed that MCM4, Clinical stage, and Tumor invasion were independent prognostic factors for OS in UCEC patients (p-value <0.05)." (PMID 35719366, 2022). "Furthermore, comparing MCM4 expression between 49 pairs of HCC tissues and adjacent tissues, a significant upregulation of MCM4 was detected in tumor tissues (p < 0.0001)." (PMID 34961841, 2021). "After screening based on the exclusion criteria, the nontumor samples or tumor samples with data deficiency were excluded, MCM4 expression information from 360 HCC tissues and 49 normal tissues was retrieved from TCGA database." (PMID 34961841, 2021). "Moreover, we validated the overexpression of MCM2 and MCM4 in NSCLC by using the fresh samples from 30 patients who had undergone tumor removal surgery in our hospital." (PMID 33936158, 2021). "However, there are also few genes like PLK1 and MCM4 that are upregulated in both zebrafish and different tumor entities." (PMID 33362851, 2020). "YWHAB, LRRC59 and MCM4 was significantly overexpressed in tumor tissue (p < 0.05)." (PMID 31387239, 2019). "However, a thorough study of the tumor phenotype of Mcm4GT/+ mice will be required to determine the threshold levels of active MCM4 that are required to maintain genomic stability and prevent tumorigenesis." (PMID 23133403, 2012). "Interestingly, elevated Mcm4 mRNA levels have been found in certain tumors, suggesting that increased Mcm4 expression can contribute to the malignant properties of the tumor cells." (PMID 17822556, 2007). "Notably, the fold change from normal to primary tumor was 3.25, indicating early involvement of MCM4 in tumorigenesis, while the additional increase in metastasis (fold change = 1.22) also reached statistical significance, supporting MCM4’s role in metastatic progression." (PMID 40564876, 2025). "Moreover, MCM4 expression was significantly higher in the invasive front than in the tumor surface." (PMID 37737200, 2023). "Therefore, MCM4 might contribute the development of characteristic histological structures in tumor invasive front, and further study will be needed on the relationship between MCM4, tumor heterogeneity and microenvironment in UC." (PMID 37737200, 2023). "Minichromosomal maintenance 4 (MCM4) belongs to the family of MCM proteins (MCMs), a group of family proteins strongly linked with DNA replication and cell proliferation, participates in the regulation of DNA replication initiation, and can be used as an effective marker for tumor diagnosis." (PMID 34961841, 2021). "Surprisingly, the MCM4 expression was also found to be associated with MCM4 copy number (p < 0.001), higher metastasis potential (p < 0.001), tumor mitotic count (p < 0.001), and worse survival outcome (p = 0.019), but not tumor necrosis rate." (PMID 34178990, 2021). "TME analysis revealed that MCM4 impacts the infiltration of immune cells (e.g., CD8+ T cells) into tumor tissues." (PMID 40959096, 2025). "This study explores the potential of MCM4 as a biomarker for SKCM and its impact on the tumor microenvironment (TME)." (PMID 40959096, 2025). "Afterwards, we assessed the correlation between MCM4 expression levels and various types of genomic alterations, including HRD, MATH, MSI, NEO, TMB, LOH, ploidy and purity, across all TCGA tumor samples." (PMID 38499612, 2024). "To further examine the molecular mechanism of the MCM4 gene in tumor development, we employed a GGI network to uncover the correlation between MCM4 and its adjacent genes." (PMID 38499612, 2024). "Our findings suggest that MCM family members play crucial roles in BC progression, and MCM2, MCM4–7, and MCM10 in tumor tissues possess great potential to be valuable prognostic biomarkers for BC patients." (PMID 34475953, 2021). "DEmRNAs, including ATAD2, KIF23, MCM4, CCNB1, and CCNE1, are highly expressed in LUAD than in corresponding non-tumor tissues." (PMID 33042838, 2020).
tumor (continued). "Our recent studies demonstrated that some passenger strands of miRNAs, e.g., miR-143-5p, miR-145-3p and miR-150-3p, behave as tumor-suppressive miRNAs in LUAD cells by targeting oncogenes, e.g., LMNB2, MCM4 and TNS4, respectively." (PMID 32932948, 2020). "Among 17 genes that were included in this panel, the expression of YWHAB, MCM4, LRRC59 and FBXO46 was found to be elevated in tumor tissue compared to normal." (PMID 31387239, 2019). "Five genes namely ZWINT, CDC7, MCM4, MCM2 and MCM6 are proposed from the comprehensive computational analysis which gets affected in neoplasia stage and are responsible for the disease progression." (PMID 30150654, 2018). "Notably, the A2 tumor area exhibited significant reductions in proteins essential to the DNA replication pathway, including MCM3, MCM4, POLD1, RFC2, and PCNA, all of which are pivotal for maintaining the integrity of DNA replication." (PMID 40076915, 2025). "To further investigate the potential role of MCM4 in LUAD invasiveness, we analyzed its expression correlation with matrix metalloproteinases (MMPs), which are known to facilitate extracellular matrix degradation and tumor metastasis." (PMID 40564876, 2025). "Key genes such as MCM4, POLA1 and MCM6 are closely related to tumor immune invasion." (PMID 39083127, 2024). "Mice implanted with blank PLA nanofiber membrane (PLA-NF) or MOF-loaded nanofiber membrane (MOF-NF) exhibited significant tumor growth, while mice implanted with cisplatin-loaded MOF (D@MOF-NF) or MCM4 siRNA-loaded membrane group (G@NF) showed a noticeable reduction in tumor size." (PMID 39290263, 2024). "We investigated MCM4 expression in UTUC and revealed that MCM4 might be a useful predictive marker for high grade, tumor progression and poor prognosis." (PMID 37737200, 2023). "Although further study is needed, these data indicate that MCM4 may be a promising predictor for HER2/EGFR targeting UC and may promote tumor progression by participating in the EGFR/HER2 signaling pathways in UC." (PMID 37737200, 2023). "As a result, the most significant positive correlations were observed between MCM4 (TG of IRF6) with both MGPS (correlation = 0.47, P = 6.7E−14) and tumor size (correlation = 0.25, P = 0.04), emphasized the important role of MCM4 in IRF6-mediated cell proliferation." (PMID 36434634, 2022). "Increased MCM4 may indicate the negative regulation by PSA expression and further hint at an elevated immunoreactivity aiming to tumour and reinforced genome stability." (PMID 33107155, 2020). "We found a significant increase in MCM2 (3.5 fold), MCM3 (3.1 fold), MCM4 (4.3 fold), MCM5 (3.8 fold), MCM6 (3.5 fold), MCM7 (3.0 fold) and MCM10 (3.6 fold) expressions in tumor tissues (the average fold value of three grades) compared to the normal brain controls." (PMID 25046975, 2014). "In a re-analysis of those data, one prominentgene-expression feature included genes regulating the cell-cycle (e.g. CCNE1,CDK1, CDC25A), and involved in DNA replication(e.g. POLE2, MCM4, TK1) andchromosome dynamics (e.g. SMC4, CENPE), ostensiblyreflecting tumor cell proliferation levels." (PMID 21629784, 2011). "For example, the MCM protein family (including MCM4, MCM6, and MCM3) plays a key role in DNA replication and cell cycle regulation and may affect tumor immune infiltration by affecting the proliferation and growth of tumor cells." (PMID 39083127, 2024). "Moreover, MCM4 and MCM6 expression are clinically relevant to tumor stage." (PMID 32021565, 2020). "For LPS, MCM4 was significantly correlated with AJCC stage, histological grade, tumor relapse-free survival, and Ki67 index (p < 0.05), but not gender, age, tumor location, etc.." (PMID 34178990, 2021). "Not all but some of the genes as MCM4, MCM6, MCM10 and RECQL4 show a positive trend with increasing tumor stages." (PMID 23874974, 2013).
adenocarcinoma (7 papers, 2016 to 2025). A common cancer characterized by the presence of malignant glandular cells. "Our analysis demonstrated that patients with high MCM4 expression level (>70%) had significantly shorter survival in the adenocarcinoma group." (PMID 27476776, 2016). "In the adenocarcinoma group, the overall survival time for patients with high MCM4 expression level (mean, 27.1 months) was statistically shorter than those with low MCM4 expression level (mean, 46.5 months) (P = .03)." (PMID 27476776, 2016). "Finally, we investigated whether the expression of MCM4, CENPI, and KNTC1 was associated with the NEPC score, which was introduced to quantify the degree of CRPC-adenocarcinoma (CRPC-Adeno) conversion to CRPC-neuroendocrine (CRPC-NE), a more aggressive variant of CRPC." (PMID 36035209, 2022). "Among them, the mRNA expression of 5 genes, namely, BIRC5, MCM4, CDC20, KIAA0101, and TRIP13, were significantly upregulated among TN adenocarcinomas (all P < 0.05)." (PMID 31093306, 2019).
infection (4 papers, 2015 to 2024). The state of being infected such as from the introduction of a foreign agent such as serum, vaccine, antigenic substance or organism. "We looked at expression of Bloom (BLM), Proliferating Cell Nuclear Antigen (PCNA) and Mini-Chromosome Maintenance 4 (MCM4) at 16, 24, 48 and 72 h after infection as compared to mock infected cells." (PMID 29257057, 2017). "Overall, infection with dl309 induced expression of BLM, MCM4, and PCNA to levels higher than dl520 infection, and with the exception of PCNA to levels similar to those observed in pm975-infected cells." (PMID 26448631, 2015). "Expression of BLM, MCM4, and PCNA was unaltered at 8 hours after infection as compared to mock-infected cells." (PMID 26448631, 2015). "Furthermore, seven genes (CDK1, TYMS, MCM5, KIF11, CCNB2, MAD2L1, and MCM4) have been identified as core hub genes involved in cell-cycle regulation, potentially serving as mediators in the pathogenesis triggered by NN1172 infection within the thymus." (PMID 38362295, 2024). "Lastly, induction of MCM4 lagged behind that of BLM and PCNA and correlated closely with initiation of viral DNA replication, with levels of MCM4 mRNA increasing at 48 h after infection in these cells." (PMID 29257057, 2017).
colon (1 paper, 2021). "Interestingly, the downregulated DEGs, such as MAD2L1, CCNA2, MCM2, MCM4, FEN1, and CDK6, were enriched in DNA replication, tyrosine metabolism, and cell cycle pathways, which are commonly upregulated in colon cancer." (PMID 34521988, 2021).
MCM4 also shares sentences with these, for which no sentence is quoted: cutaneous melanoma (3 papers); immune deficiencies (3); Immunodeficiency 54 (3); dysplasia (2); Fanconi anaemia (2); immunodeficiencies (2); leiomyosarcoma (2); liver disease (2); malignant fibrous histiocytoma (2); myxofibrosarcoma (2); oral squamous cell carcinoma (2); skin cancer (2); synovial sarcoma (2); adrenocortical cancer (1); Autoimmunity (1); Burkitt lymphoma (1); cervical intraepithelial neoplasia (1); Cirrhosis (1); dedifferentiated liposarcoma (1); desmoid fibromatosis (1); Dystonia (1); ectodermal dysplasia (1); endometrial endometrioid adenocarcinoma (1); endometrial mixed adenocarcinoma (1); endometrial serous adenocarcinoma (1); esophageal tumor (1); FILS syndrome (1); head and neck squamous cell carcinoma (1); herpesvirus infections (1); hypogonadism (1).
A further 27 diseases each share a sentence with MCM4 in 1 paper.